HOXA9 (homeobox A9)
Diseases named in the same sentence as HOXA9 in open-access papers (continued):
Sharing a sentence is not in itself a finding about the gene and the disease.
leukemia (continued). "Indeed, the relevance of HOXA9 expression in global survival of human leukemia patients was first demonstrated on gene expression signatures relating to patient outcome: HOXA9 was evidenced as the protein presenting the highest correlation with poor prognosis in a series of nearly 7000 genes." (PMID 31213012, 2019). "This compound potently inhibits the expression of MLL-fusion target genes HOXA9 and MEIS1, selectively inhibits the proliferation of MLL-rearranged leukemia cells (IC50 = 3.5 nM), and causes complete and sustained regression in a rat xenograft model of MLL-rearranged leukemia." (PMID 31817960, 2019). "Therefore, HOXA9 might be an attractive therapeutic target for leukemia patients with a constitutive HOXA9 expression, such as MLL-related leukemia, as it is mostly dispensable for normal development of hematopoietic progenitors." (PMID 28471392, 2017). "PFI-1 and JQ1 dissociate BRD4 from HOXA9 and promotes differentiation, as a marker of poor prognosis in patients with acute myeloid leukemia and overexpression of HOXA9 leads to expansion of hematopoietic stem cells in bone marrow cells and development of leukemia in mice." (PMID 25849938, 2015). "It reportedly takes 3 to 10 months for Hoxa9-transduced BM to give rise to leukemia after the transplantation, which appears to be compatible with the hypothesis that Hoxa9 transduction induces genomic instability to trigger the second hits as well as provides proliferation potential." (PMID 23326393, 2013). "Importantly, HoxA9 expression alone (but not Meis1 alone) can cause leukemia in mice, although with a much longer latency than HoxA9/Meis1 co-transfected mice, and it is required for MLL-ENL mediated bone marrow transformations." (PMID 24213472, 2012). "KMT2A-rearranged leukemias characteristically exhibit marked upregulation of homeobox A (HOXA) genes, especially HOXA9, which are central to leukemic transformation." (PMID 40374809, 2025). "More importantly, the overexpression of FLT3 significantly restored the cell expansion in the RBM5 sgRNA-treated leukemia cells, similar to the extent of both RBM5 and HOXA9 overexpression." (PMID 38216972, 2024). "We define the in vivo hierarchy of Hoxa9-driven AML and identify a population that we term the “LIC-e” (leukemia initiating cells enriched) population." (PMID 39004675, 2024). "In leukemia, HBO1 upregulates HOXA9 and HOXA10 expression through H3K14 acetylation, maintaining leukemia stem cell characteristics." (PMID 39543485, 2024). "We report here that Phf6 knockout increases the aggressiveness of Hoxa9-driven AML over serial transplantation, and increases the frequency of leukemia initiating cells." (PMID 39004675, 2024). "The integrative analysis further suggested that the HOXA9/FLT3 axis promises the dominant downstream target of RBM5, as demonstrated by functional rescue assay and transcriptional regulation in leukemia cells." (PMID 38216972, 2024). "The role of HOXA9 in binding to noncoding regulatory sequences and regulates the downstream genes in MLL gene rearrangements (MLL-r) leukemia." (PMID 38016946, 2023). "The system itself was confirmed to be a powerful tool for identifying downstream targets of HOXA9 that represent potential therapeutic targets for MLL-r and potentially for other HOXA9-driven leukemia." (PMID 38016946, 2023). "We demonstrate the downstream functional effectors of HOXA9 and provide additional clues to identify potential therapeutic targets in MLL-r leukemia." (PMID 38016946, 2023). "Concordant with our findings, previous studies have identified the co-upregulation of HOXA9 and MEIS1 in KMT2A-rearranged leukemias and further support that these TFs are key drivers of leukemogenesis." (PMID 38116118, 2023). "Inspired by these studies, we established the HA-tag-based HOXA9 ChIP-seq using an inducible expression system and identified 229 reproducible HOXA9-bound peaks in MLL-r leukemia cell lines." (PMID 38016946, 2023).
leukemia (continued). "Selected inhibitors were found to suppress expression of MLL target genes HoxA9, Meis1 and Myc and inhibit proliferation of MLL-r leukemia and other AML cells with EC50s as low as 4.7 μM, while they were inactive against solid tumor Hela cells." (PMID 37958457, 2023). "In MLL-fused leukemia cells, the RELA-p50 complex binds to MLL1 and induces trimethylation of histone H3K4 residues in the promoter regions of HOXA9 and MEIS1." (PMID 36362853, 2022). "In the mixed-lineage leukemia cell line MOLM-13, the HOXA9 gene is in a 100 kb broad H3K79me2 domain with other HOXA protein-coding and oncogenic long non-coding RNA genes." (PMID 36139405, 2022). "It is thought that small molecule Menin-MLL inhibitors inhibit MLL-FP-induced leukemia by disrupting the Menin-MLL interaction and inhibiting Menin/MLL induced HOXA9 gene." (PMID 36376832, 2022). "SYC-522, a potent DOT1L inhibitor, was developed to inhibit the methylation at H3K79, decrease the expression of HOXA9 and MEISI and raise the sensitivity of MLL-rearranged leukemia cells presenting a potential means to treat MLL-rearranged leukemia." (PMID 36376832, 2022). "HOXA9/MEIS1 are essential co-factors for KMT2A-driven leukemogenesis, making it possible that a CDX2-HOXA9/MEIS1 axis exerts a similar leukemia promoting role in UBTF::ATXN7L3 ALL." (PMID 35397658, 2022). "We also observed the aberrant overexpression of MEIS1 and HOXA9, members of the same family as MEIS3, that is highly effective in transforming hematopoietic progenitors and driving mice toward a lethal leukemia." (PMID 36002858, 2022). "How compound 1-mediated ENL degradation changes expression of HoxA9, Meis1 and Myc, three characteristic genes in MLL1-r leukemia, was examined." (PMID 35395864, 2022). "Several chemical agents that disrupt HOXA9 function, such as HXR9 peptide inhibitor and heterocyclic diamidine DNA ligands, are being used as potential leukemia treatments." (PMID 35743243, 2022). "We analysed which TFs are predicted to be enriched in MLL-AF9 blasts and revealed a set of TFs that are well documented to have a role in MLL-AF9 leukemias, such as MECOM (EVI1), but also HOXA9, and HOXA76,49." (PMID 36333382, 2022). "This set of target genes was also confirmed in leukemias induced in mice transformed by MLL-AF9 (HoxA9, HoxA10, Evi1 (MECOM), HoxA2, HoxA7 HoxA3, and HoxA13) and also induced iMLL-AF9 in mice HoxA9, HoxA10, Meis1, Eya1, Mef2c, Myb, and Six1." (PMID 34639154, 2021). "DOT1L has been found to be required for expression of MLL1-target genes such as HoxA9 and Meis1 and therefore a drug target for MLL1-r leukemia." (PMID 33823889, 2021). "Co-expression of FOXC1 with Hoxa9 accelerates the onset of AML in murine modeling, with the resulting leukemias exhibiting a higher level of differentiation block by comparison with those initiated by Hoxa9 alone." (PMID 34551306, 2021). "Next, we assessed the effects of the combined expression of MYC, HOXA9, and MEIS1 in mouse leukemia models." (PMID 34310280, 2021). "It is widely proven that MLL-AF4 binds to the HOXA9 promoter and activates the transcription of this gene in MLL-related leukemia." (PMID 33924850, 2021). "In the case of MLL fusion-mediated leukemia, MLL fusion proteins directly activate both MYC and HOXA9, while HOXA9 maintains expression of MYC, BCL2, and SOX4, achieving high MYC activity and anti-apoptotic properties simultaneously." (PMID 34310280, 2021). "Depletion of this transcriptionally activating mark by DOT1L deletion or high concentrations of the inhibitor pinometostat downregulates HOXA9 and MEIS1, and consequently reduces leukemia survival." (PMID 34263728, 2021). "The HoxB5, HoxA9, and Meis1 oncogenes were inserted into ML-23 leukemic cell line DNA, which suggests that they were involved in inducing AML-like leukemia in our model." (PMID 33602907, 2021).
leukemia (continued). "In human leukemia, the cooperation between MEIS1 and HOXA9 with PBX has been extensively reported; specifically, the PBX3 form appears to be the prevalent form involved." (PMID 34698191, 2021). "Mechanistically, these anti-leukemia effects of I-BET151 are likely due to its suppression of ZM-activated pro-leukemic genes, including Hoxa7, Hoxa9, Meis1, Myc and Myb." (PMID 33594072, 2021). "We also show that stimulation of leukemia cells with FGF2 increases nuclear level of FGFR2 in its phosphorylated form, as well as HOXA9 and MEIS1 expression." (PMID 33924850, 2021). "In PBX-MEIS1-induced human leukemia and in MEIS1-dependent mouse tumorigenesis, HOXA9 appears to have an accelerating role." (PMID 34698191, 2021). "On the other hand, Bcl2 deletion delayed the onset of leukemia induced by MLL-AF10 and the HOXA9/MEIS1 combination in vivo." (PMID 34310280, 2021). "In agreement with the previous evidence that reduced expression of HOXA9 and MEIS1 impairs viability of leukemia cells, FGFR2 knockdown negatively affected the proliferative rate of RS4;11 leukemia cells." (PMID 33924850, 2021). "Studies in mammals have shown that NA9 transformation and leukemia-promoting activity depends on the FG-rich repeats of NUP98 and the DNA-binding activity of the HOXA9 homeodomain." (PMID 34383740, 2021). "Another leukemia study showed that KMT2D occupied and activated pro-tumorigenic HOXA9 target genes and that KMT2D was required for leukemogenesis mediated by co-expression of HOXA9 and MEIS1in vivo." (PMID 34194626, 2021). "We previously found that loss of Kmt2a led to downregulation of the aberrant “MN1-driven leukemic program”, suggesting that the aberrant expression of Hoxa9 and Meis1 in MN1-driven leukemia remained under the control of its physiologic regulator, Kmt2a." (PMID 33542482, 2021). "Knowing that DOT1L primarily drives Hoxa9 and Meis1 expression for the initiation and maintenance of MLL-AF9 leukemia, we expected that with decreased H3K79me2, we would see a profound decrease in expression of MLL target genes." (PMID 33562706, 2021). "Both HOXA9 and HOXA10 were reported to be highly expressed and significantly correlated with leukemia progression and/or maintenance." (PMID 33037410, 2020). "Additionally, the CHASE-knock-in protocol developed to generate the HOXA9 reporter is user-friendly, highly efficient, robust to reproduce and could be easily adapted to a wide variety of HOXA9-driven human leukemia cell models and other HOXA9-expressing cancer types." (PMID 33001025, 2020). "For example, in MLL-rearranged leukemia, the MLL oncogene promoted myeloid transformation genetically relies on HOXA7 and HOXA9." (PMID 31013831, 2019). "In addition, a novel NUP98 partner gene for HOXA13, with an expression pattern similar to HOXA9 in leukemic cell lines, implies that the NUP98-HOXA13 fusion protein, like the NUP98-HOXA9 fusion protein, may play a role in leukemia development via the same mechanism." (PMID 31426381, 2019). "This was directly confirmed by quantitative RT-PCR, whereby we demonstrated that CCI-006, unlike CCI-007, did not decrease the mRNA expression of leukemogenic MLL target genes HOXA9 and MEIS1 in MLL-r leukemia cells." (PMID 30670779, 2019). "Together, this demonstrates unique dependency on a subset of the Hoxa cluster (Hoxa7, Hoxa9, Hoxa10, and Hoxa11) genes for maintenance of MA9 leukemia." (PMID 31861091, 2019). "This is due to its involvement in elevating transcription of leukaemia-relevant genes, such as MEIS and HOXA9, which is achieved by its interaction with MLL-fusion oncoproteins and the resultant epigenetic modification of such genes by H3K79 methylation." (PMID 31882723, 2019). "Conversely, the PLXND1, PLCB4, HOXA9, HOXA10, TLX3, and NKX2‐1 genes had higher expression in the CIMP+ subgroup, compared to the normal T cells and CIMP− leukemias." (PMID 30575306, 2019).
leukemia (continued). "NCD38, a tranylcypromine-based LSD1 inhibitor that impairs growth of the MLL-AF9-positive leukemia cell model MOLM14, reduces HOXA9 expression and induces myeloid differentiation." (PMID 31213012, 2019). "If MEIS1 potentiates the leukemia action of HOXA9, this is also the case of PBX3, whose expression is also strongly correlated with HOXA9 expression, especially in leukemia subtypes with a normal karyotype or associated with MLL rearrangements." (PMID 31213012, 2019). "CCI-006 treatment increased the levels of CHOP mRNA and phosphorylated JNK (p-JNK) and diminished the levels of HOXA9, MEIS1, and CMYC, important leukemogenic drivers and survival factors for MLL-r leukemia in sensitive MLL-r leukemia cells." (PMID 30670779, 2019). "To evaluate the consequences for the transcriptome of co-expression of IRX3 with Hoxa9, we performed RNA sequencing of flow-sorted KIT+Gr1+ leukemia cells recovered from the BM of sick mice, three from each cohort." (PMID 29346763, 2018). "Accordingly, leukemic cells carrying the BCR–ABL, MLL–AF9 fusion proteins, and co-expressing HoxA9 and Meis1 were all affected by the inactivation of Pml in MSCs, thus suggesting the possibility that the same therapeutic intervention could be beneficial in multiple leukemia sub-types." (PMID 29302031, 2018). "Recent genome-wide ChIP-seq analyses identified various sets of direct target genes of MLL-FP, which consistently included the master regulatory factors (HOXA7, HOXA9, HOXA10, and MEIS1) required for the development of MLLr-leukemias." (PMID 29692408, 2018). "Murine Hoxa9/FOXC1 leukemias also exhibited shortened latency versus Hoxa9/MTV leukemias, in contrast to the latencies observed for Hoxa9/IRX3 leukemias." (PMID 29346763, 2018). "Among these MLL targets genes, such as HOXA9 and MEIS1, it is well established the crucial role played in MLL-induced leukemia, however many other of the genes strongly deregulated by MLL fusion proteins remain poorly characterized." (PMID 28412727, 2017). "Treatment with these MLLi led to down-regulation of gene-expression programs enforced by MLL fusion, such as HOXA9 and MEIS1, in the leukemia cells." (PMID 29075615, 2017). "Different from GMP-derived leukemias induced by Setbp1 and BCR/ABL, Hoxa9+BCR/ABL and Hoxa10+BCR/ABL leukemias are mostly monoclonal in origin, suggesting that additional mutation(s) is likely required for the transformation in both cases." (PMID 29228732, 2017). "When miR-196b was over-expressed in leukaemia cells, it represses the function of FAS and at the same time promotes cell proliferation and inhibits apoptosis via increases expression of HOXA9/MEIS1." (PMID 28458781, 2017). "Our results also suggest that Hoxa9 is more potent than Hoxa10 in inducing CML myeloid blast crisis, as the Hoxa9+BCR/ABL mice developed leukemia with a significantly shorter latency than Hoxa10+BCR/ABL mice." (PMID 29228732, 2017). "Resembling mice with Hoxa9+BCR/ABL and Hoxa10+BCR/ABL leukemias, the bone marrow, spleen and liver of the moribund mice were infiltrated by immature leukemia blasts, representing 31 ± 5.7% (Mean ± SD) of all nucleated cells in the bone marrow." (PMID 29228732, 2017). "In summary, our results identify overexpression of HOXA9, HOXA10, and MYB as critical drivers of CML progression, and suggest MYB as a key therapeutic target for inhibiting the self-renewal of leukemia-initiating cells in CML myeloid blast crisis patients." (PMID 29228732, 2017). "Consistent with DOT1L loss-of-function studies, these DOT1Li also selectively inhibited expression of MLL-fusion target genes such as HOXA9 and MEIS1 and selectively killed MLL-rearranged leukemia cells and xenografted tumors." (PMID 29075615, 2017). "MLL-r leukemia is characterised by deregulated gene expression that reportedly entails increased expression levels of HOXA9, MEIS1, CMYC and BCL2, which have been suggested to play important roles in MLL-r leukemia cell survival." (PMID 27317766, 2016).
leukemia (continued). "In leukemias, miR-150-5p act as a tumor suppressor in MLL-rearranged and other subtypes of acute myeloid leukemia (AML), by targeting HOXA9 and MEIS1, either directly or indirectly." (PMID 27447965, 2016). "Our lab previously found that MSI2 directly binds to the mRNA of mixed-lineage leukaemia target genes including Hoxa9, Myc and Ikzf2, and regulates the translation of these targets in a mixed-lineage leukaemia-AF9 leukaemia model." (PMID 26898884, 2016). "CCI-007 altered the characteristic MLL-r gene expression signature in sensitive cells with downregulation of the expression of HOXA9, MEIS1, CMYC and BCL2, important drivers in MLL-r leukemia, within a few hours of treatment." (PMID 27317766, 2016). "In myeloid leukemias, MYB has been shown to be a critical target of known oncogenes, including HOXA9 and MLL fusions, and has been identified as a part of a leukemia stem cell maintenance signature." (PMID 27863435, 2016). "All mice that received Bcl-2+/+ cells transduced with HoxA9/Meis1 or MLL-AF9 developed rapid and aggressive leukemia with an average latency of 40 days." (PMID 24177192, 2013). "An earlier study showed DOT1L to be essential for HOXA9 and MEIS1 expression and the resulting leukemia driven by MLL-AF9." (PMID 23847761, 2013). "HoxA9 overexpression is a feature of leukemia with MLL rearrangements, trisomy 8 and the t(7:11)(p15:p15) translocation that fuses the homeodomain of HoxA9 to Nup98." (PMID 24177192, 2013). "Human leukemias with MLL rearrangements are strongly correlated with expression of the MEIS1 and HOXA9 genes." (PMID 24213472, 2012). "HOXA9 is frequently induced in human AML with poor prognosis and Hoxa9 can induce leukemia in murine BM transplantation models in collaboration with Meis1 similar to what we have shown for ND13 and NA10." (PMID 17712416, 2007). "Further, our data showed a dampening effect of SMAD1 presence combined with TGF-β stimulation on the expression of the two KMT2A-rearranged leukemia-driving genes HOXA9 and MEIS1, which has not been described in literature yet." (PMID 39834944, 2024). "Furthermore, leukemia co-expressing KDM3C and HOXA9 contributes to tumor aggressiveness by demethylase-independent upregulation of glycolytic and oxidative metabolism." (PMID 38926399, 2024). "Although inhibiting the upstream regulators of HOXA9 has been proven as a significant therapeutic intervention, the comprehensive regulation network controlling HOXA9 expression in leukemia has not been systematically investigated." (PMID 38216972, 2024). "To further explore the underlying molecular mechanism, we performed transcriptome analysis with and without HOXA9 overexpression (HOXA9 OE) in the RBM5 knockout leukemia cells." (PMID 38216972, 2024). "Given that 70% of human AMLs show high HOXA9 levels, we deemed the Hoxa9 overexpression mouse model as being broadly relevant to human leukemia biology, as opposed to MLL-AF9, which does not co-occur with PHF6 mutation in humans." (PMID 39004675, 2024). "Moreover, while the blockage of HOXA9, an KMT2A downstream target, sensitizes KMT2A‐r leukemia to PARP inhibitors and impairs DDR, the overexpression of HOXA9 rather confers PARP inhibitor resistance to AML1‐ETO and PML‐RARα transformed cells." (PMID 39428967, 2024). "Moreover, compound 1 counteracted two critical transcription factors HoxA9 and Myc in MLL1-r leukemia: treatment with compound 1 reversed expression patterns of HoxA9-regulated genes." (PMID 35395864, 2022). "However, during leukemia, the abnormally high expression of FOXC1 in AML and the interaction between HOXA5/HOXA9, members of the Hox family, can lead to abnormal myeloid differentiation." (PMID 35504885, 2022). "Sox4 deletion also delayed the onset of HOXA9/MEIS1-induced leukemia, although it did not affect MLL-AF10-induced leukemia." (PMID 34310280, 2021). "As with HOXA9, NA9-induced leukemia is accelerated by co-expression of MEIS1." (PMID 34383740, 2021).